CIROP (ciliated left-right organizer metallopeptidase)
Description:
Putative metalloproteinase that plays a role in left-right patterning process.
Synonyms: LMLN2; HTX12
Gene: Protein-coding gene on chromosome 14 (23,099,062 to 23,105,018, reverse strand). Ensembl gene ENSG00000283654.
Subcellular location: Membrane
Gene Ontology:
Molecular function: peptidase activity; metalloendopeptidase activity
Biological process: establishment of left/right asymmetry; cell adhesion; proteolysis
Cellular component: cytoplasm; membrane
Homologues: Orthologues: chimpanzee CIROP (99% identical), macaque CIROP (94% identical), dog CIROP (74% identical), rabbit CIROP (73% identical), mouse Cirop (66% identical), rat Cirop (65% identical), tropical clawed frog CIROP (34% identical), zebrafish cirop (29% identical).